NOTCH1 (notch receptor 1)
Diseases named in the same sentence as NOTCH1 in open-access papers (continued):
Sharing a sentence is not in itself a finding about the gene and the disease.
depression (8 papers, 2016 to 2025). "This study investigates the role of HMGB1 in anxiety and depression-like behaviors associated with the microglial Notch1/Hes-1 pathway in CRS mice." (PMID 39789446, 2025). "NOTCH1 also showed associations with anxiety and depression symptoms in our sample of sexual abuse victims." (PMID 27959334, 2016). "Our overall findings provide preliminary evidence that NOTCH1 may be implicated in the susceptibility to anxiety and depression among sexual abuse victims." (PMID 27959334, 2016). "Thus, our findings implicating NOTCH1 gene in susceptibility to anxiety and depression among sexual abuse victims should be further examined in larger samples, using clinically validated mood phenotypes." (PMID 27959334, 2016). "Both tag SNPs of NOTCH1 gene revealing associations with anxiety and depression symptoms in this study, as well as variants in high linkage disequilibrium with them, showed regulatory potential by displaying both enhancer and promoter properties in brain tissue, including hippocampus." (PMID 27959334, 2016). "Furthermore, our results implicate the NOTCH1 system in the susceptibility to comorbid anxiety and depression symptoms in a sample of sexually abused individuals." (PMID 27959334, 2016). "HMGB1 appears to trigger neuroinflammation by activating the Notch1/Hes-1 pathway in hippocampal microglia, contributing to the emergence of anxiety and depression-like symptoms." (PMID 39789446, 2025). "Drawing on prior research, our investigation will focus on the effects of HMGB1 and the Notch1/Hes-1 pathway on anxiety and depression symptoms in CRS, as well as their mechanisms within hippocampal microglia." (PMID 39789446, 2025). "In this study, compared to the control group, CRS mice with anxiety and depression showed significantly increased expression levels of Notch1/Hes-1, TNF-α, IL-1β, and IL-6 in the hippocampal region." (PMID 39789446, 2025). "Cluster 5 included NOTCH1 and NOTCH2, which may be associated with depression and anxiety-like behaviors." (PMID 41157308, 2025). "These clusters particularly involved genes related to regulatory subunits of cAMP-dependent protein kinases, such as PRKAR2A, cAMP-responsive element-binding pathway, circadian rhythms, such as CLOCK, ARNT1, CRY2, PER1, and PER2, and anxiety and depression, such as NOTCH1, NOTCH2 and ANK2." (PMID 41157308, 2025). "Regarding its implication with the hippocampus, NOD2, like NOTCH1, may be related to anxiety, as in the case of depression." (PMID 34072914, 2021). "Specifically, minor alleles of two NOTCH1 tag SNPs—rs3013302 and rs11145770—were associated with higher likelihood of displaying comorbid anxiety and depression symptoms compared with not displaying these symptoms in a sample of sexual abuse victims." (PMID 27959334, 2016). "The main finding of the present study was the implication of NOTCH1 as a candidate gene for the pathomechanisms following early-life stress that may be relevant for the development of anxiety and depression in humans who experienced sexual abuse." (PMID 27959334, 2016). "This study confirms that CRS mice exhibit symptoms of anxiety and depression, with elevated HMGB1 expression and stimulation of the Notch1/Hes-1 pathway in hippocampal microglia." (PMID 39789446, 2025). "HMGB1 activates the microglial Notch1/Hes-1 pathway in CRS mice, promoting neuroinflammation and anxiety and depression-like behaviors." (PMID 39789446, 2025). "Moreover, Notch1 imbalances have been evidenced in patients and animal models affected by psychoses, such as SCZ, depression and anxiety." (PMID 35732696, 2022). "Not surprisingly, dysregulation of NOTCH1 signaling has been mechanistically linked to the dentate gyrus- and hippocampus-related pathologies present after TBI, including epilepsy via gliosis, stress and depression via neurogenesis, and learning and memory deficits via synaptic plasticity." (PMID 28273100, 2017).
epilepsy (8 papers, 2012 to 2025). A brain disorder characterized by episodes of abnormally increased neuronal discharge resulting in transient episodes of sensory or motor neurological dysfunction, or psychic dysfunction. "The function of Pin1 in epilepsy may be associated with some classical signaling pathways, such as the Notch1 signaling and PI3K/Akt signaling pathways." (PMID 36304997, 2022). "In summary, BAO alleviates KA-induced epilepsy-like behaviors by modulating the Notch1/GABA/GAD/GIRK signaling pathway, thereby exerting a therapeutic effect on epilepsy." (PMID 41011202, 2025). "In terms of epilepsy, Notch1 signaling has the ability to induce astrogliosis in glioma, which is critical in the occurrence of epilepsy." (PMID 36304997, 2022). "Overall, the Notch1 signaling pathway is significant in the pathogenesis of epilepsy." (PMID 36304997, 2022). "Therefore, we can hypothesize that the interaction between Pin1 and Notch1 pathway may play a role in epilepsy and that Notch1 may participate in epileptogenesis via the function of CaMKII and PKA." (PMID 36304997, 2022). "In summary, BAO mitigates KA-induced epilepsy-like behaviors by modulating the Bcl2/Bax/caspase-3 signaling pathway and the Notch1/GABA/GAD/GIRK signaling pathway, thereby playing a therapeutic role in epilepsy." (PMID 41011202, 2025). "We could find that BAO could regulate Notch1 through MAP 2 and NMDAR 1 to attenuate the KA-induced epilepsy-like behavior." (PMID 35445130, 2022). "Meanwhile, we had to admit that Notch1 also has been identified participating in the regulation of central neurogenesis or neuroplasticity, thus we cannot rule out their possible influences on epilepsy via other signaling pathways and mechanisms." (PMID 39136073, 2024). "Furthermore, BAO could regulate the expression of GABA, NMDAR1, Notch1, and MAP2 to improve the symptoms of epilepsy." (PMID 35445130, 2022).
hypoplastic left heart syndrome (8 papers, 2020 to 2023). Hypoplastic left heart syndrome (HLHS) refers to the abnormal development of the left-sided cardiac structures, resulting in obstruction to blood flow from the left ventricular outflow tract. "Pathogenic NOTCH1 mutations are linked to severe forms of CHDs such as hypoplastic left heart syndrome (HLHS) and tetralogy of Fallot." (PMID 33178704, 2020). "Also, a recent exome sequencing study of 49 patients with hypoplastic left heart syndrome reported rare truncating variants in NOTCH1 as conveying significant risk for left ventricular outflow tract obstruction." (PMID 33110418, 2020). "For example, hiPSCs derived from a hypoplastic left heart syndrome (HLHS) patient with Notch1 mutations in the extracellular and intracellular domains exhibit Notch1-dependent nitric oxide (NO) signaling deficiency and impaired cardiogenesis." (PMID 34677194, 2021). "Some organoid models have been touted as new tools to study several congenital and developmental disorders such as hypoplastic left heart syndrome (HLHS) where the left ventricle fails to form due to mutation in NOTCH1 gene." (PMID 35317745, 2022).
anaplastic large cell lymphoma (7 papers, 2013 to 2024). Anaplastic large cell lymphoma (ALCL) is a rare and aggressive peripheral T-cell non-Hodgkin lymphoma, belonging to the group of CD30-positive lymphoproliferative disorders, which affects lymph nodes and extranodal sites. "Non-mutated Notch1 is highly expressed in Hodgkin lymphoma (HL) and anaplastic large cell lymphoma (ALCL) cells, and tumor-associated JAG1, overexpressed by bystander cells as well as by neighboring tumor cells, induces Notch1 activation and promotes tumor cell proliferation and survival." (PMID 25309874, 2014). "Interestingly Notch1 is frequently expressed in anaplastic large cell lymphoma (ALCL) cells, and Notch signaling appears to induce proliferation and survival." (PMID 24959528, 2014).
ascending aortic aneurysm (7 papers, 2012 to 2023). "Later studies by the same group, however, reported that Notch1 haploinsufficiency in 129SV mice also causes ascending aortic aneurysm, making the role of Nos3 in aortopathy less clear." (PMID 32801116, 2020). "Furthermore, genetic variation in the NOTCH1 gene appears to confer susceptibility to ascending aortic aneurysm formation in patients with BAV." (PMID 23300792, 2012). "Using clinical samples, our protein analysis also indicated that patients with BAV-TAA presented lower expression of NOTCH1 protein in ascending aortic aneurysms; and the NOTCH1 insufficiency was accompanied with attenuated mitochondrial fusion." (PMID 34486519, 2021). "Here, we investigated if a deregulation of Notch1 signaling pathway and endothelial progenitor cells (EPCs) number is associated with BAV disease and an early ascending aortic aneurysm (AAA) onset." (PMID 30218064, 2018). "Furthermore, genetic variation in NOTCH1 appears to confer susceptibility to ascending aortic aneurysm formation in patients with BAV but not in patients with TAV." (PMID 23300792, 2012).
brain cancer (7 papers, 2013 to 2022). A primary or metastatic malignant neoplasm affecting the brain. "We assessed multiple patient datasets to probe the clinical relevance Notch1 activation and possible differential distribution amongst molecular subtypes in brain cancers." (PMID 33004830, 2020). "Previous studies showed PDGF-D facilitated tumor invasion and metastasis by activating Notch1, PI3K, ERK, or CXCR4 pathways in breast, lung and brain cancers." (PMID 28035069, 2017).
carcinoid (7 papers, 2017 to 2024). "In a pilot phase II clinical trial, our group demonstrated that the Notch1 mRNA upregulation post valproic acid treatment, a known HDAC inhibitor, was associated with improved outcomes in patients with carcinoid tumors." (PMID 29050323, 2017). "ASCL1 is overexpressed in ileal NETs and in vitro experiments have shown that transient overexpression of Notch1 in carcinoid cell lines can reverse ASCL1 overexpression, indicating that Notch1 activation may be a potential therapeutic strategy." (PMID 38539512, 2024). "Primary carcinoid S1 showed one private somatic mutation in the CDK12 gene (p.Arg44Leu), whereas the adenocarcinoma component of metastatic site showed a private mutation in the NOTCH1 gene (p.Pro498Arg)." (PMID 34926584, 2021). "Previously, it was reported that VPA could directly stimulate NOTCH1 in carcinoid tumors." (PMID 34226515, 2021). "In ileal NETs, ASCL1 is overexpressed and transient overexpression of Notch1 in carcinoid cell lines in vitro can reverse ASCL1 overexpression, suggesting that activation of Notch1 may be therapeutic." (PMID 29255447, 2017). "The supra-carcinoids were negative for DLL3 expression, and had generally high-expression levels of NOTCH1-3." (PMID 31431620, 2019).
cutaneous squamous cell carcinoma (7 papers, 2010 to 2026). "Genes that are recurrently mutated in cutaneous squamous cell carcinoma are also frequently mutated in sun-exposed epidermis and the location of mutations within the NOTCH1 gene in our samples closely parallels that seen in cutaneous squamous cell carcinoma." (PMID 29066762, 2017). "This may be in line with the observation that inactivating mutations in NOTCH1, or loss of NOTCH1 due to deletions, occur early in the development of cutaneous squamous cell carcinomas." (PMID 33430387, 2021). "Similarly, conditional NOTCH1-knockout (mice) develop cutaneous epithelial tumors, and transgenic mice expressing a pan-NOTCH1 inhibitor develop cutaneous squamous cell carcinomas." (PMID 26528858, 2016). "The intent of this study was to evaluate the expression patterns of the NOTCH1 and FGFR2 genes and to explore potential correlations between them across successive histological stages of cutaneous squamous cell carcinoma." (PMID 39063983, 2024). "In our study, we observed distinct expression patterns of NOTCH1 and FGFR2 across different histological stages of cutaneous squamous cell carcinoma (cSCC)." (PMID 39063983, 2024). "While our study provides significant insights into the expression patterns of NOTCH1 and FGFR2 in cutaneous squamous cell carcinoma (cSCC), there are several limitations to consider." (PMID 39063983, 2024).
glomerular diseases (7 papers, 2010 to 2024). "Conditional inactivation of Notch1 and its transcriptional targets in both early and late stages of Wt1 glomerulopathy would further define the role and window for Notch activation in disease pathogenesis." (PMID 29398135, 2018). "The protein VEGF has been reported to be closely related to podocyte deletion, and could be upregulated by Notch-1 signaling activation in many glomerular diseases." (PMID 30237561, 2018).
intrahepatic cholangiocarcinoma (7 papers, 2014 to 2026). A carcinoma that arises from the intrahepatic bile duct epithelium in any site of the intrahepatic biliary tree. "HIPPO/YAP1 signalling is also implicated in Ang II-mediated proliferation in intrahepatic cholangiocarcinoma (iCCA), with ARBs disrupting AGTR1+ cancer-associated fibroblast (CAF) MFAP5/Notch1 signalling by impeding YAP/TEAD nuclear translocation and reducing tumour proliferation." (PMID 41408463, 2026). "In intrahepatic cholangiocarcinoma (iHCC), losartan reduced stromal density by inhibiting YAP1/LAT1 dephosphorylation and MFAP5-mediated Notch1 signalling from AT1R+ CAFs." (PMID 41408463, 2026).
invasive ductal carcinoma (7 papers, 2013 to 2025). "Notch1 expression is significantly associated with invasive ductal carcinoma, lymphatic metastasis and histological grade." (PMID 26121683, 2015). "This meta-analysis showed a correlation of NOTCH1 mRNA expression with invasive ductal carcinoma, lymphatic metastasis and histological grading." (PMID 39153127, 2025). "The NOTCH1 signaling pathway is possibly involved in the negative association of the ALDH1A1 phenotype with early malignant relapse in invasive ductal carcinoma." (PMID 23767668, 2013). "Our findings collectively suggest a possible negative association of the ALDH1A1 phenotype with NOTCH1 in invasive ductal carcinoma." (PMID 23767668, 2013). "Therefore, in the present study, we hypothesized that NOTCH1 might be a prognostic marker of invasive ductal breast carcinoma." (PMID 28330128, 2016). "Even though the role of Notch 2 remains ambiguous, similarly to Notch 1, represents an oncogenic factor in HER2 and basal subtype invasive ductal carcinoma (IDC) breast cancer, while it is a tumor-suppressor in ER+ luminal and TNBC cell lines." (PMID 35406423, 2022). "Notch 1 has an oncogenic function in estrogen receptors (ER) luminal cell lines, tumor negative breast cancer (TNBC) and in invasive ductal carcinoma." (PMID 35406423, 2022).
lymphocytic leukemia (7 papers, 2011 to 2023). "The NOTCH1 is known to be associated with leukemogenesis in lymphocytic leukemias and has been reported more frequent in AML than MDS and showed poor patient’s survival." (PMID 35396491, 2022). "Next to the oncogenic potential of MLL rearrangement via ZNF521 or EVI1, which enhances AML transformation, NOTCH1 upregulation is known to be particularly relevant in lymphoid leukemia such as T-ALL or chronic lymphocytic leukemia (CLL) and is associated with a poor prognosis." (PMID 37833915, 2023).
medullary thyroid cancer (7 papers, 2017 to 2023). "Of particular importance is that miR-182 reveals its oncogenic capacity in medullary thyroid carcinoma by directly contributing to the invasive behavior through loss of the tumor suppressive HES1/Notch1 signaling circuit." (PMID 28122586, 2017). "MiR-182 has an oncogenic role in medullary thyroid carcinoma through regulation of the HES1/NOTCH1 axis." (PMID 37051101, 2023). "In cancer, several pathways might be dysregulated, and combinatory therapy with LiCl and pharmacological activators of the Notch1 pathway suppressed the hormonal secretion and reduces cell growth through apoptosis in medullary thyroid cancer (MTC)." (PMID 36836894, 2023). "Additionally, a novel histone deacetylase with anti-Notch1 characteristics is currently in a phase I clinical trial as a potential therapy for medullary thyroid cancer (NCT01013597)." (PMID 29152142, 2017).
ventricular septal defect (7 papers, 2018 to 2024). The presence of a defect (opening) in the septum that separates the two ventricles of the heart. "Previously, we found matDM interacts with Notch1 haploinsufficiency in mice to increase the incidence of membranous ventricular septal defects (VSDs), supporting a GxE between Notch1 and matDM." (PMID 39437002, 2024). "For example, different variants in NOTCH1 have been observed in several types of CHD, such as pulmonary stenosis (PS), left ventricular outflow tract obstructive, and ventricular septal defect." (PMID 35872895, 2022). "Our Case 2 carried a 9q34.3 microdeletion surrounding full-length NOTCH1, and presented underdeveloped left heart and ventricular septal defect." (PMID 33898534, 2021).
acute leukemia (6 papers, 2016 to 2023). A clonal (malignant) hematopoietic disorder with an acute onset, affecting the bone marrow and the peripheral blood. "In the murine SCL-LMO1 transgenic model, progression to acute leukemia is driven by the acquisition of Notch1 gain-of-function mutations, starting at 7–8 weeks of age, reproducing a major feature of the human disease." (PMID 35589701, 2022). "The NOTCH1 pathway plays a critical role in the pathogenesis of many cancers including acute leukemia." (PMID 37833915, 2023). "Notch1 signaling activation promotes proliferation in adult acute leukemia cells and regulates hepatic glucose production and lipid synthesis." (PMID 36860568, 2023). "In adult acute leukemia, JAG1 overexpression contributed to the Notch1 signaling pathway and the migration of HTLV‐1 ‐transformed ATL cells." (PMID 36860568, 2023). "In summary, our genetic approach indicates that in the absence of a hyperactive NOTCH1 and of pre-TCR signaling, progression to acute leukemia in SCL-LMO1-induced T-ALL involves the downregulation of a tumor suppressor network implicating HEB and p21CDKN1A." (PMID 35401501, 2022).
Anxiety (6 papers, 2016 to 2025). Intense feelings of nervousness, tension, or panic often arise in response to interpersonal stresses. "This study found that CRS mice with severe anxiety-depressive symptoms had significantly increased hippocampal expression levels of Notch1/Hes-1, indicating the importance of microglial Notch1/Hes-1 pathway activation." (PMID 39789446, 2025). "siRNA knockdown of HMGB1 in microglia significantly reduced Notch1/Hes-1 pathway proteins and inflammatory factors, highlighting HMGB1’s role in activating the Notch1/Hes-1 pathway and contributing to anxiety-depressive-like behaviors in CRS mice." (PMID 39789446, 2025). "Significant associations were noted for four SNPs in the GABRR1 gene and one SNP in the NOTCH1 gene when comparing the ‘No symptoms' to the ‘Anxiety only' group." (PMID 27959334, 2016).
aortic coarctation (6 papers, 2012 to 2024). "A number of studies support the association of variants in the NOTCH1 gene not only with BAV but with other cardiovascular abnormalities such as ascending aortic dilation and aortic coarctation." (PMID 39057646, 2024).
chronic kidney disease (6 papers, 2012 to 2025). Impairment of the renal function secondary to chronic kidney damage persisting for three or more months. "Notch1 was shown to be up-regulated in the patients with chronic kidney disease characterized by low expression of e-cadherin and high expression of collagen-1 associated with EMT induction." (PMID 37414855, 2023). "Notch1 activity was elevated in fibrotic kidneys of rat models and patients with chronic kidney disease (CKD)." (PMID 31718671, 2019).